LTBP4 (latent transforming growth factor beta binding protein 4)
Diseases named in the same sentence as LTBP4 in open-access papers (continued):
Sharing a sentence is not in itself a finding about the gene and the disease.
breast carcinoma (6 papers, 2013 to 2023). "Knockdown of LTBP4 in mice was associated with the development of epithelial carcinoma, and the expression of LTBP4 was lower in esophageal cancer and mammary carcinoma than in normal tissues." (PMID 34359790, 2021). "The extracellular matrix protein latent TGF-β binding protein 4 (LTBP4) is downregulated in human and murine ductal carcinomas in situ, invasive mammary carcinomas, as well as in canine mammary carcinomas, indicating a possible phylogenetic conserved regulation of LTBP4 expression." (PMID 23741501, 2013). "The potential target genes of miR-1908-3p in breast cancer included ID4, LTBP4, GPM6B, RGMA, EFCAB1, ALX4, OSR1 and PPARA." (PMID 32650755, 2020). "Interestingly, eight genes (ID4, LTBP4, GPM6B, RGMA, EFCAB1, ALX4, OSR1 and PPARA) were confirmed to be down-expressed in breast cancer tissues, and associated with the overall survival time of breast cancer patients, as high expression of these genes correlate with an improved prognosis." (PMID 32650755, 2020). "Importantly, increases in COL8A1, BGN, COL11A1, POSTN, MMP11 and SORCS2 and decreased LTBP4, PCOLCE2, LRRC17 and SDK1 have been identified in CAS and CAFs from human breast cancer and are consistently perturbed in stroma of canine and human mammary cancer." (PMID 37391533, 2023). "Based on these findings, a potential miR-1908-3p-mRNA regulatory network, miR-1908-3P-ID4/ LTBP4/ GPM6B/ RGMA/ EFCAB1/ ALX4/ OSR1/ PPARA, contributing to breast cancer onset and progression could be established." (PMID 32650755, 2020). "Our analysis of stromal changes between non-metastatic and metastatic canine mammary carcinomas highlighted molecular differences in the tumour microenvironment, including changes in VIT, TGFBR2, TGFBR3, LTBP4 and SFRP1." (PMID 37391533, 2023).
colorectal cancer (5 papers, 2010 to 2025). A primary or metastatic malignant neoplasm that affects the colon or rectum. "SNPs in LTBP4 have also been associated with reduced expansion of abdominal aortic aneurysm, and less aggressive tumors in colorectal cancer." (PMID 26918958, 2016). "An increase in LTBP4 expression might potentially cause colorectal cancer development." (PMID 20459617, 2010). "Silencing of LTBP4 promoted invasion and migration of the cells, suggesting that LTBP4 plays a role also in colorectal cancer." (PMID 29416670, 2018). "To examine the function of LTBP4 in colorectal cancer, we knocked down LTBP4 expression in a colon cancer cell line SW480 by siRNA and performed an invasion assay." (PMID 29416670, 2018). "The postnatal role of LTBPs, including LTBP4, may be quite distinct and the molecular interactions in differentiated cell types may account for the effect in chronic lung disease, abdominal aneurysms and in colorectal cancer." (PMID 26918958, 2016). "The protective LTBP4 haplotype correlates with milder disease in DMD, better exercise performance in chronic lung disease, smaller abdominal aneurysms and less invasive colorectal cancer." (PMID 26918958, 2016).
colon cancer (3 papers, 2016 to 2025). "In particular, we confirmed that silencing LTBP4 promotes invasion of a colon cancer cell line." (PMID 29416670, 2018).
heart failure (3 papers, 2015 to 2022). Inability of the heart to pump blood at an adequate rate to meet tissue metabolic requirements. "Chance of progression to heart failure would be a major factor in evaluating the risk/benefit balance of protracted steroid treatment, especially in the non-ambulatory phase, and our data suggest that LTBP4 genotyping might be of aid to clinicians in stratifying risks." (PMID 26513582, 2015).
lung carcinoma (3 papers, 2014 to 2025). "In the TCGA cohort, the AUC values ​​of CBLC, FABP4, GDF10, and LTBP4 genes were 0.982, 0.997, 0.980, and 0.983, respectively, indicating that these genes have a high diagnostic efficiency in distinguishing lung cancer samples from normal control groups." (PMID 40766337, 2025). "In an independent external sequencing sample cohort, these genes also performed impressively, with the AUC value for CBLC at 0.800, while the AUC values for FABP4, GDF10, and LTBP4 all reached 1.000, further validating their potential as diagnostic markers for lung cancer." (PMID 40766337, 2025). "The identification of LTB4R, LTBP4, MPI, and TCN2, in conjunction with PSMA4, highlights the intricate heterogeneity of lung cancer and underscores the necessity for tailored therapeutic strategies." (PMID 39529882, 2024).
pulmonary fibrosis (3 papers, 2016 to 2021). Chronic progressive interstitial lung disorder characterized by the replacement of the lung tissue by connective tissue, leading to progressive dyspnea, respiratory failure, or right heart failure. "Reduced angiogenesis, attributed to a lack of LTBP4, has been reported in pulmonary interstitial fibrosis with impaired alveolarization." (PMID 34645813, 2021). "In addition, ER stress can promote the protein expression of LTBP1 and LTBP4, which are closely related to the secretion of TGF-β1 and TGF-β4 in pulmonary epithelial cells, thereby playing a key role in the development of pulmonary fibrosis." (PMID 33097029, 2020).
scleroderma (3 papers, 2021 to 2024). Scleroderma is a rare autoimmune connective tissue disorder characterized by abnormal hardening of the skin and, sometimes, other organs. "Ltbp4/LTBP4 is involved in both elastogenesis and the regulation of TGFβ signaling, and an increase in Ltbp4 is associated with fibrosis in scleroderma via TGF-β/SMAD signaling." (PMID 37111549, 2023).
abdominal aortic aneurysm (2 papers, 2016). Enlargement and ballooning of the vessel that supplies arterial blood to the abdomen, pelvis and legs. "Data from four geographically distinct case control studies showed that sizes and growth rate of abdominal aortic aneurysm significantly correlate with the presence of a particular LTBP4 single-nucleotide polymorphism (LTBP4 21011A>T genotype)." (PMID 27585882, 2016). "An enhanced growth rate of abdominal aortic aneurysms was linked to several intronic SNPs in LTBP4 including rs3786527, rs2369006, rs7259067, rs2278242, and a borderline association with the presence of abdominal aortic aneurysms was found for synonymous SNP rs2077407." (PMID 26918958, 2016).
dilated cardiomyopathy (2 papers, 2016 to 2024). Cardiomyopathy which is characterized by dilation and contractile dysfunction of the left and right ventricles. "We stratified based on self-identified ethnicity and found that the LTBP4 VTTT allele is associated with increased risk of dilated cardiomyopathy in European Americans extending the diseases that associate with LTBP4 genotype." (PMID 26918958, 2016). "We now evaluated LTBP4 nsSNPs in dilated cardiomyopathy, a distinct disorder associated with TGFβ signaling." (PMID 26918958, 2016). "Particularly, LTBP4 and ACTN3 polymorphisms and genotypes have been proposed to be associated with a higher risk of dilated cardiomyopathy." (PMID 39342355, 2024).
dystrophinopathy (2 papers, 2015 to 2019). "Recently, the UDP group published the result of a GWAS of the age at LoA in the same cohort (UDP severe dystrophinopathy), in which the LTBP4 association was originally described." (PMID 31083420, 2019).
ectopia lentis (2 papers, 2013 to 2024). "The N164S residue substitution, which is associated with dominant ectopia lentis, perturbed binding of the FUN-EGF4 fragment to LTBP-4." (PMID 24035709, 2013). "Similarly, the ectopia lentis phenotype in LTBP2-null mice can be rescued by overexpressing the structurally related protein LTBP4." (PMID 39768188, 2024).
esophageal cancer (2 papers, 2013 to 2021). A primary or metastatic malignant neoplasm involving the esophagus. "The present study investigates the protein expression of the extracellular matrix protein LTBP4 in different stages of esophageal cancer progression, as well as in various adenocarcinomas of the gastrointestinal tract." (PMID 23741501, 2013). "Re-expression of LTBP4 in esophageal cancer cell lines reduced cell migration ability, whereas cell viability and cell proliferation remained unchanged." (PMID 23741501, 2013). "Furthermore, we investigated the potential regulatory mechanism responsible for LTBP4 inactivation in esophageal cancer." (PMID 23741501, 2013). "After demethylation treatment with 5-aza-2’-deoxycytidine LTBP4 expression was induced in OE33 and KYSE180 cells by more than 150% and 60%, respectively, whereas demethylation treatment with 5-aza-2’-deoxycytidine did not significantly change TGF-β1 expression in both esophageal cancer cell lines." (PMID 23741501, 2013).
fibrosis (2 papers, 2016 to 2023). the formation of excess fibrous connective tissue in an organ or tissue in a reparative or reactive process. "Notably, large amounts of two members of LTBPs (LTBP1 and LTBP4) were found deposited in the ECM of patients with stage F3 fibrosis." (PMID 26998606, 2016).
glioblastoma (2 papers, 2018 to 2024). The most malignant astrocytic tumor (WHO grade IV). "Mutations in LTBP4 are common in recurrent glioblastoma, and silencing of LTBP4 impairs the proliferation of glioma cell lines." (PMID 29416670, 2018). "The LTBP4 gene drives the expression of proteins upstream of TGF-β that play a role in glioblastoma cell proliferation and migration." (PMID 38928445, 2024). "Importantly, recurrent glioblastomas acquire new mutations following initial chemoradiation, including mutations in DNA mismatch repair (MMR) genes MSH6, MLH, and LTBP4." (PMID 38928445, 2024). "Accordingly, this review first aims to summarize current research in recurrent glioblastoma such as the molecular pathways and genetic mutations that drive cell proliferation (TERT, PTEN, PI3K/Akt, MSH6, and LTBP4) and paracrine signaling of glioma stem cells (GSCs)." (PMID 38928445, 2024). "Also, recurrent glioblastomas often harbor mutations in the latent TGF-binding protein 4 (LTBP4) gene, commonly absent in newly diagnosed glioblastoma-matched samples." (PMID 38928445, 2024). "On the other hand, acquired hypermethylation of mismatch repair genes MSH6, LTBP4, and ALKBH5 are almost exclusively observed in recurrent glioblastoma post-initial treatment." (PMID 38928445, 2024).
glioma (2 papers, 2018 to 2019). A benign or malignant brain and spinal cord tumor that arises from glial cells (astrocytes, oligodendrocytes, ependymal cells). "Therefore, which gene, such as HDAC7, ERCC1, LTBP4 and ZNF383, could play a major role in glioma proliferation need further study and investigation." (PMID 30691485, 2019).
Marfan syndrome (2 papers, 2024 to 2025). A disorder of the connective tissue. "Altered MFAP4 glycosylation could potentially affect binding to elastogenic proteins, including fibrillin-1 or LTBP4 isoforms, possibly affecting formation and maintenance of microfibrils and elastic fibres, which are compromised in Marfan syndrome." (PMID 38740766, 2024). "In regard to heritable connective disorders, several single reports of Marfan syndrome (MFS) with CDH have been described in the literature, and CDH is reported in 34% of the patients with arterial tortuosity syndrome and in several reports of LTBP4-cutis laxa." (PMID 41010011, 2025).
melanoma (2 papers, 2021 to 2023). A malignant, usually aggressive tumor composed of atypical, neoplastic melanocytes. "Our previous results showed that LTBP4 was not only significantly down-regulated in melanoma tumor tissues, but also served as a diagnostic marker for melanoma in the GSE46517 dataset." (PMID 35252214, 2021). "As shown by the results of RT-PCR and Western blotting assays, LTBP4 was significantly down-regulated in cancer tissues from 76 patients with melanoma, which was associated with invasion, TNM stage, distal metastasis, and lymph node metastasis." (PMID 35252214, 2021). "Among them, LTBP4 was identified as a diagnostic marker of melanoma (AUC = 0.985)." (PMID 35252214, 2021). "Next, further experimental results indicated that LTBP4 showed significantly lower expression in tumor tissues from melanoma patients and melanoma cell lines." (PMID 35252214, 2021). "Next, changes in the expression of cleaved caspase-3, Ki67, and E-cadherin proteins within melanoma cell lines with LTBP4 knockdown or overexpression were determined by Western blotting." (PMID 35252214, 2021). "The downregulation of LTBP4 is found in melanoma tissues and cell lines, which predicts poor survival of patients with melanoma." (PMID 35252214, 2021). "Down-regulation of LTBP4 expression was identified in melanoma tissues and cells, which predicted poor prognosis of patients with melanoma." (PMID 35252214, 2021). "Subsequently, we found that LTBP4 expression was significantly down-regulated in melanoma cell lines, as evidenced by RT-PCR and Western blotting assays." (PMID 35252214, 2021). "Cox analysis results discovered that LTBP4 with low expression was an independent prognostic factor for overall survival in patients with melanoma." (PMID 35252214, 2021). "Further, as indicated by tumor formation study of nude mice, LTBP4 silencing improved the tumorigenic ability of melanoma cells." (PMID 35252214, 2021). "We divided the 76 melanoma patients into high and low LTBP4 expression groups according to the average LTBP4 expression level (average = 1.925)." (PMID 35252214, 2021). "Univariate Cox proportional hazards analyses of LTBP4 expression and overall survival for patients with melanoma." (PMID 35252214, 2021). "As revealed by cell and animal studies, LTBP4 silencing promoted cell proliferation, invasion, and migration, inhibited cell apoptosis, and significantly enhanced the tumorigenicity of melanoma cells, which in turn inhibited the progression of malignant melanoma." (PMID 35252214, 2021). "LTBP4 silencing promotes the growth and metastasis of melanoma in vivo and in vitro." (PMID 35252214, 2021). "Likewise, the LTBP4 protein expression was significantly downregulated in melanoma tissues, as revealed by IHC staining." (PMID 35252214, 2021). "Knockdown of LTBP4 increased the percentage of active TGFβ1 secreted by melanoma cells." (PMID 35252214, 2021). "YAP1 has been shown to contribute to melanoma progression, therefore, we wondered whether LTBP4 affected YAP1 activity." (PMID 35252214, 2021). "LASSO analysis and SVM-RFE analysis identified LTBP4 as a key feature biomarker for melanoma." (PMID 35252214, 2021). "Correlation between LTBP4 expression and clinicopathological parameters of patients with melanoma." (PMID 35252214, 2021). "The expression levels of LTBP4 and CDHR1 in melanoma tissues were notably lower than those in the control group, while MARCKSL1 expression in melanoma tissues was notably higher than that in the control group." (PMID 35252214, 2021). "Meanwhile, the functions of LTBP4 overexpression in inhibiting the expression of cleaved caspase-3 and E-cadherin and inhibiting that of Ki67, CTGF, Cyr61 and Birc5 in melanoma cells were abolished by YAP1 overexpression or MST1 overexpression." (PMID 35252214, 2021).
melanoma (continued). "In addition, the effects of LTBP4 overexpression on inhibiting CTGF, Cyr61 and Birc5 expression, promoting the apoptosis, and inhibiting the metastasis and proliferation of melanoma cells were reversed by the overexpression of YAP1 or MST1." (PMID 35252214, 2021).
renal fibrosis (2 papers, 2021 to 2023). A final common manifestation of a wide variety of chronic kidney diseases characterized by glomerulosclerosis and tubulointerstitial fibrosis. "Herein, we created a renal fibrosis model in an Ltbp4S−/− mouse in an attempt to investigate the mechanisms underlying LTBP4/TGFβ signalling and elucidate the impact of LTBP4 on the pathogenesis of renal tubular interstitial fibrosis (TIF)." (PMID 34645813, 2021). "entitled “LTBP4 (Latent Transforming Growth Factor Beta Binding Protein 4) Protects Against Renal Fibrosis via Mitochondrial and Vascular Impacts” uncovers LTBP4's renoprotective role against acute kidney injury via modulating mitochondrial dynamics." (PMID 37960979, 2023). "Clarification of the precise role of LTBP4 in mitochondrial structure and function, and the contribution of this mechanism to the pathogenesis of renal fibrosis will require further investigations." (PMID 34645813, 2021). "It remains unclear if pathways of LTBP4 in other tissue systems, such as those causing DMD, may relate to these pathways involved in renal fibrosis." (PMID 37960979, 2023). "Collectively, our findings indicate that LTBP4 protects against disease progression and may be of therapeutic use in renal fibrosis." (PMID 34645813, 2021). "Thus, LTBP4 antagonized the differentiation of fibroblasts into myofibroblasts, a process that plays a major role in renal fibrosis development." (PMID 34645813, 2021). "Transforming growth factor beta (TGFβ) signalling regulates extracellular matrix accumulation known to be essential for the pathogenesis of renal fibrosis; latent transforming growth factor beta binding protein 4 (LTBP4) is an important regulator of TGFβ activity." (PMID 34645813, 2021). "To date, the regulation of LTBP4 in renal fibrosis remains unknown." (PMID 34645813, 2021). "The complexity of LTBP4 functions might provide a novel target for the treatment of renal fibrosis." (PMID 34645813, 2021). "However, there were no obvious difference in IFN-γ expression between WT and Ltbp4S−/− mice, suggesting that LTBP4 deficiency did not affect IFN-γ production in renal fibrosis." (PMID 34645813, 2021). "Previously, Su and colleagues discovered that LTBP4 is upregulated in CKD and participates in resolving renal fibrosis." (PMID 37960979, 2023).
respiratory failure (2 papers, 2015 to 2021). The significant impairment of gas exchange within the lungs resulting in hypoxia, hypercarbia, or both, to the extent that organ tissue perfusion is severely compromised. "Both ARCL1C patients and LTBP4 deficient mice have high postnatal mortality due to respiratory failure caused by severely disrupted pulmonary elastic fibre architecture, indicating a crucial role for LTBP4 in elastic fibre assembly." (PMID 34539739, 2021).
sarcopenia (2 papers, 2016 to 2023). Progressive decline in muscle mass due to aging which results in decreased functional capacity of muscles. "While further research is needed, sarcopenia, or the age‐related loss of muscle mass, has been linked to myostatin levels, establishing LTBP4 as a potential therapy for sarcopenia." (PMID 37960979, 2023). "Because LTBP4 binds GDF11 in vitro, it is possible that muscle specific LTBP4 overexpression could alter sarcopenia or other aging related phenotypes." (PMID 27148972, 2016).
acute myocardial infarction (1 paper, 2021). Necrosis of the myocardium, as a result of interruption of the blood supply to the area. "One study of left ventricular dysfunction after acute myocardial infarction reported a panel of three genes (TNXB, TGFBR1, and LTBP4) that could potentially improve the prediction of post-myocardial infarction heart failure." (PMID 34071145, 2021).
aortic aneurysm (1 paper, 2021). A ruptured aneurysm located in the wall of the proximal portion of the descending aorta proceeding from the arch of the aorta. "Immunofluorescent microscopy was used for determining the deposition of proteins known to play a role in aortic aneurysms in humans: fibrillin-1 (FBN1), latent transforming growth factor beta binding protein 4 (LTBP4) and fibronectin." (PMID 34607531, 2021).
asthma (1 paper, 2022). "Of the lung function candidate genes, rare variant burden in four genes (MAPT, CFDP1, EML3, and LTBP4) was nominally associated with asthma risk in our study." (PMID 35368043, 2022).
carcinoma in situ (1 paper, 2013). "Cancer adjacent normal tissue displayed 43%, hyperplasia 22%, carcinoma in situ 8%, EAC 37%, small cell undifferentiated carcinoma 3%, ESCC 4% and distant metastasis 4% LTBP4 expression in comparison to normal esophageal tissue." (PMID 23741501, 2013).